CERS6-AS1 (CERS6 antisense RNA 1)
Gene: Long non-coding RNA gene on chromosome 2 (168,771,951 to 168,786,961, reverse strand). Ensembl gene ENSG00000227617.
Diseases named in the same sentence as CERS6-AS1 in open-access papers:
CERS6-AS1 is named in the same sentence as 2 diseases in open-access papers, as found by Europe PMC text mining. Sharing a sentence is not in itself a finding about the gene and the disease. The quoted sentences say what the papers report.
breast carcinoma (1 paper, 2021). "The long non-coding RNA CERS6 antisense RNA 1 (CERS6-AS1) has critical regulatory roles in breast cancer progression." (PMID 33581689, 2021). "The lncRNA CERS6 antisense RNA 1 (CERS6-AS1) plays critical regulatory roles in breast cancer progression." (PMID 33581689, 2021).
pancreatic cancer (1 paper, 2022). "Although lncRNA could interact with miR-15a-5p in diseases, such as the regulatory mechanism of lncRNA CERS6 antisense RNA 1 and miR-15a-5p in pancreatic cancer, the relationship between AFAP1-AS1 and miR-15a-5p in EMS is rarely reported in existing works." (PMID 35513844, 2022).